SYT13 (synaptotagmin 13)
Description:
May be involved in transport vesicle docking to the plasma membrane.
Synonyms: KIAA1427
Tractability: Small molecule: it has a high-quality binding pocket. Antibody: UniProt predicts a signal peptide or a membrane-spanning region; its Gene Ontology location is reachable by antibodies, with medium confidence.
Gene: Protein-coding gene on chromosome 11 (45,240,302 to 45,286,341, reverse strand). Ensembl gene ENSG00000019505.
Subcellular location: Membrane
Subcellular location (Human Protein Atlas): Vesicles
Gene Ontology:
Molecular function: calcium ion sensor activity; calcium-dependent phospholipid binding; SNARE binding
Biological process: calcium-dependent activation of synaptic vesicle fusion; regulation of calcium ion-dependent exocytosis; regulation of synaptic vesicle exocytosis; vesicle-mediated transport
Cellular component: transport vesicle; axon; dense core granule; exocytic vesicle; plasma membrane; synaptic vesicle membrane; membrane
Genetic constraint (gnomAD): Loss-of-function variants: 21 observed, 38.94 expected, observed/expected ratio (o/e) 0.54, 90% interval 0.38 to 0.78. The upper end of that interval is the gene's LOEUF score, 0.78, which puts it in group 3 of 6, group 1 being the genes least tolerant of losing a copy. Missense variants: 495 observed, 544.93 expected, observed/expected ratio (o/e) 0.91, 90% interval 0.84 to 0.98. Synonymous variants: 241 observed, 233.48 expected, observed/expected ratio (o/e) 1.03, 90% interval 0.93 to 1.15.
Homologues: Orthologues: chimpanzee SYT13 (99% identical), macaque SYT13 (99% identical), pig SYT13 (93% identical), dog SYT13 (92% identical), rabbit SYT13 (92% identical), mouse Syt13 (90% identical), rat Syt13 (90% identical), guinea pig SYT13 (81% identical), tropical clawed frog syt13 (44% identical), zebrafish syt13 (43% identical), Drosophila melanogaster Sytbeta (27% identical). Paralogues in human: SYT6 (29% identical), SYT10 (26% identical), SYT9 (26% identical), SYT1 (25% identical), SYT2 (24% identical), SYT3 (24% identical), SYT5 (23% identical), SYT17 (22% identical), SYT7 (22% identical), SYT8 (22% identical), SYT12 (21% identical), SYT4 (20% identical), and 19 more.
Diseases named in the same sentence as SYT13 in open-access papers:
SYT13 is named in the same sentence as 29 diseases in open-access papers, as found by Europe PMC text mining. Sharing a sentence is not in itself a finding about the gene and the disease. The quoted sentences say what the papers report.
gastric cancer (10 papers, 2019 to 2025). A primary or metastatic malignant neoplasm involving the stomach. "Our group previously found that intraperitoneal injection of SYT13 siRNA inhibited the peritoneal dissemination of gastric cancer in mouse models, and that SYT13 expression was an independent risk factor for peritoneal recurrence in patients with gastric cancer." (PMID 34677264, 2021). "For this purpose, we designed and synthesized ASOs targeting the mRNA encoding the transmembrane vesicular trafficking protein SYT13 that mediates synapsis and vesicle metabolism, which we previously identified as a driver of peritoneal metastasis of gastric cancer." (PMID 33230476, 2020). "Therapeutic development targeting SYTs is progressing, with an antisense oligonucleotide targeting SYT13 currently advancing to preclinical trials for gastric cancer." (PMID 40576306, 2025). "For instance, silencing the synaptotagmin XIII (SYT13) gene using siRNA significantly reduces the invasive and migratory capabilities of gastric cancer cells." (PMID 37663132, 2023). "SYT13 knockdown decreased proliferation and metastasis of lung adenocarcinoma cells and gastric cancer cells." (PMID 36522312, 2022). "The tumor-promoting roles of SYT13 have been reported in various malignant tumors, such as lung adenocarcinoma and colorectal and gastric cancers." (PMID 34677264, 2021). "For example, in gastric cancer, SYT13 is involved in the progression of peritoneal metastasis and thus is a potential therapeutic target." (PMID 34677264, 2021). "We designed 71 sequences, and to screen for optimal ASOs, we compared their abilities to inhibit SYT13 mRNA expression in gastric cancer cell lines." (PMID 33230476, 2020). "We recently reported that synaptotagmin XIII (SYT13) contributes to peritoneal metastasis of gastric cancer." (PMID 33230476, 2020). "Intra-abdominal administration of AmNA-modified anti-SYT13 ASOs represents a promising strategy for treating the peritoneal metastasis of gastric cancer." (PMID 33230476, 2020). "We reasoned therefore that intraperitoneal administration of AmNA-modified anti-SYT13 ASOs transfected using CEM represents a promising technique for treating peritoneal metastasis of gastric cancer." (PMID 33230476, 2020). "In the present study, we demonstrate the inhibitory effect of AmNA-modified anti-SYT13 ASOs on peritoneal metastasis of gastric cancer in vitro and in vivo using the CEM method (simple adjustment of the CaCl2 concentration of the ASO solution)." (PMID 33230476, 2020). "We aimed to develop an intraperitoneal treatment strategy using amido-bridged nucleic acid (AmNA)-modified antisense oligonucleotides (ASOs) targeting synaptotagmin XIII (SYT13) and to identify the function of SYT13 in gastric cancer cells." (PMID 33230476, 2020). "Here, we describe two lines of evidence that identify the function of SYT13 in gastric cancer cells and indicate that AmNA-modified, SYT13-specific ASOs show promise for treating peritoneal metastasis of gastric cancer." (PMID 33230476, 2020). "Our present knockdown experiments using ASOs reveal that SYT13 controls cellular functions during each stage of seed formation, such as proliferation, invasion, migration, and adhesion of gastric cancer cells." (PMID 33230476, 2020). "We believe that it is reasonable to conclude that knockdown of SYT13 expression will serve as an effective therapy for inhibiting the proliferation of metastatic gastric cancer cells that populate the peritoneum." (PMID 33230476, 2020). "Intra-abdominal administration of AmNA-modified anti-SYT13 ASOs represents a promising strategy for treating peritoneal metastasis of gastric cancer." (PMID 33230476, 2020). "As IP chemotherapy is required to increase the concentration of drugs in peritoneal tumors, the intra-abdominal administration of amido-bridged nucleic acid-modified anti-SYT13 ASOs represents a promising strategy for treating peritoneal metastasis of gastric cancer." (PMID 37537633, 2023).
gastric cancer (continued). "Genes such as SYT13 and BCYRN1 were responsible for invasion and migration of many cancer cells such as gastric cancer and lung cancer, but these genes may be associated with invasion and migration of GBM cells." (PMID 31137733, 2019). "The tumor-promoting roles of synaptotagmin 13 (SYT13) have been studied in various malignant tumors, including lung adenocarcinoma and colorectal and gastric cancers, and higher SYT13 expression has been shown to be a poor prognostic factor." (PMID 34677264, 2021). "To propose a novel treatment option for patients with peritoneal metastasis of gastric cancer, we designed amido-bridged nucleic acid (AmNA)-modified antisense oligonucleotides (ASOs) targeting synaptotagmin XIII (SYT13)." (PMID 33230476, 2020). "Our results indicate potentially complex interactions between SYT13 and the PI3K-AKT-mTOR pathway, which likely contribute to enhancing the survival of gastric cancer cells." (PMID 33230476, 2020). "In contrast, the SYT13-specific siRNA showed little in vitro inhibitory effect on the proliferation of gastric cancer cells in the presence of 9 mM CaCl2, in the absence of transfection agents." (PMID 33230476, 2020).
breast carcinoma (4 papers, 2021 to 2023). "Furthermore, SYT13 is overexpressed in both clinical specimens and cell lines of estrogen receptor (ER)-positive breast cancer." (PMID 36004367, 2022).
lung adenocarcinoma (4 papers, 2021 to 2024). A carcinoma that arises from the lung and is characterized by the presence of malignant glandular epithelial cells. "It has been reported that SYT13 is up-regulated in the lung adenocarcinoma as well as in colorectal cancer, which promotes the proliferation and migration of lung adenocarcinoma cells and colorectal cancer cells and contributes to an unsatisfactory prognosis." (PMID 34229539, 2021). "In lung adenocarcinoma, SYT13 contributes to cellular proliferation, clonality, and anti-apoptotic effects, and in colorectal cancer, silencing SYT13 inhibits tumor growth in mouse models." (PMID 34677264, 2021). "Syt13 was another gene downregulated in both tissues (p-value<0.05) with a role in neurotransmitter secretion by synaptic vesicles but also recently characterized in human as a biomarker in lung adenocarcinoma, consistent with smoking exposure." (PMID 39574597, 2024).
amyotrophic lateral sclerosis (3 papers, 2021 to 2024). Amyotrophic lateral sclerosis (ALS) is a neurodegenerative disease characterized by progressive muscular paralysis reflecting degeneration of motor neurons in the primary motor cortex, corticospinal tracts, brainstem and spinal cord. "Accordingly, the transcriptome of SYT13+/− cultures significantly correlated with the Amyotrophic Lateral Sclerosis annotation and was characterized by significantly lower levels of the biomarker NfH than SYT13+/+ ones." (PMID 39097602, 2024). "Overexpression of SYT13 was found to preserve motor neurons and delay muscle denervation and improve survival and lifespan in mice affected with amyotrophic lateral sclerosis and spinal muscular atrophy, which are lethal neurodegenerative diseases." (PMID 36292693, 2022). "Moreover, Syt13 plays a protective function in motor neurons of patients with amyotrophic lateral sclerosis (ALS) and spinal muscular atrophy (SMA)." (PMID 34830411, 2021).
motor neuron diseases (3 papers, 2020 to 2025). "A striking aspect is SYT13’s protective effects across different genetic causes of motor neuron disease." (PMID 39813104, 2025). "Thus, Syt13 delivery was protective across motor neuron diseases that arise from distinct genetic causes." (PMID 32065260, 2020). "Our results suggest Syt13 as a promising candidate for future therapeutic interventions in motor neuron diseases." (PMID 32065260, 2020). "On the basis of these considerations and of the striking transcriptional phenotype displayed by SYT13+/− MNs, it is somehow surprising that this gene has not been causally linked to major motor neuron diseases." (PMID 39097602, 2024). "Thus, our approach of using degeneration-resistant OMNs as a tool to identify motor neuron-protective molecules was validated and identified SYT13 as a candidate therapeutic target for motor neuron diseases." (PMID 32065260, 2020). "Thus, SYT13 is a resilience factor that can protect motor neurons and a candidate therapeutic target across motor neuron diseases." (PMID 32065260, 2020). "Finally, we examined if the delivery of Syt13 to transgenic SMA∆7 mice could positively affect their disease phenotype and be protective across motor neuron diseases." (PMID 32065260, 2020).
asthma (2 papers, 2020 to 2024). "Lastly, Syt13’s potential impact on cytokine release through vesicular trafficking highlights the complex network of genes influencing T cell behavior and the pathophysiology of asthma, allergies, and inflammation, offering insights into potential therapeutic targets for these conditions." (PMID 39345572, 2024).
astrocytoma (1 paper, 2024). "KIAA1045 (PHD finger protein 24) and SYT13 (Synaptotagmin 13) genes have been recognized as hubs in 2021 astrocytoma, but the average of their 2016 percentage measures is 4 and 8, respectively." (PMID 39286768, 2024).
cervical cancer (1 paper, 2022). A primary or metastatic malignant neoplasm involving the cervix. "Among the upregulated genes, SYT13 (synaptotagmin 13) expression was significantly higher in cervical cancer tissues (n = 306) than that in normal cervical tissues (n = 13)." (PMID 36522312, 2022). "SYT13 is upregulated in cervical cancer patients, and its overexpression correlated with poor overall survival." (PMID 36522312, 2022). "Together, ESM1 overexpression-induced PI3K-Akt activation as well as cervical cancer cell invasion/ migration might be due to increasing SYT13 expression." (PMID 36522312, 2022). "Here, the bioinformatics studies and RNA sequencing data revealed that SYT13 could be a primary target of ESM1 in cervical cancer." (PMID 36522312, 2022). "In addition, SYT13 mRNA expression was much higher in cervical cancer cells than that in cervical epithelial cells." (PMID 36522312, 2022). "Ectopic ESM1 overexpression in cervical cancer cells increased SYT13 expression." (PMID 36522312, 2022). "SYT13 silencing potently inhibited ESM1-overexpression-induced PI3K-Akt cascade activation and cervical cancer cell migration/invasion." (PMID 36522312, 2022). "Significantly, SYT13 was upregulated in ESM1-overexpressed SiHa and HeLa cervical cancer cells (OE-ESM1)." (PMID 36522312, 2022). "Our present study implied ESM1-driven cervical cancer cell progression and EMT by mediating SYT13-dependent activation of PI3K/Akt cascade." (PMID 36522312, 2022). "Therefore, ESM1-driven cervical cancer progression could be due to promoting SYT13 expression." (PMID 36522312, 2022). "SYT13 siRNA suppressed migration and invasion of both vector control and ESM1-overexpressed cervical cancer cells." (PMID 36522312, 2022). "Importantly, SYT13 silencing potently inhibited ESM1-overexpression-induced PI3K-Akt activation and cervical cancer cell migration/invasion." (PMID 36522312, 2022). "Whereas siRNA-induced silencing of SYT13 decreased PI3K-Akt cascade in cervical cancer cells, without affecting ESM1 expression." (PMID 36522312, 2022). "Moreover, SYT13 mRNA expression was increased in cervical cancer tissues compared to that in the adjacent noncancerous tissues." (PMID 36522312, 2022).
Cognitive impairment (1 paper, 2025). Abnormal cognition is characterized by deficits in thinking, reasoning, or remembering. "Maintaining SYT13 protein levels in cells by targeting α-Syn oligomers could thus be a promising therapeutic avenue, with particular potential for the treatment of the cognitive impairment associated with synucleinopathies." (PMID 40551252, 2025). "The findings of the present study further suggested that the synaptic dysfunction resulting from aberrant interactions between toxic β-sheet-rich α-Syn oligomers and SYT13 may explain some of the underlying causes of cognitive impairment associated with synucleinopathies." (PMID 40551252, 2025).
colorectal tumor (1 paper, 2024). "In this context, repression of SYT13 inhibits tumor growth and induces apoptosis in colorectal tumor cells." (PMID 39097602, 2024).
Hepatic steatosis (1 paper, 2020). Steatosis is a term used to denote lipid accumulation within hepatocytes. "Although the inhibitory effect on the formation of peritoneal metastasis and suppression of SYT13 expression in tumor nodules was concentration dependent, liver damage was caused by ≥0.2 mg hSYT13-4378, and hepatic steatosis occurred at the maximum dose (0.6 mg), which debilitated the mice." (PMID 33230476, 2020).
Sepsis (1 paper, 2023). Sepsis is defined as life-threatening organ dysfunction caused by a dysregulated host response to infection. "The role of SYT13 in sepsis still unknown, whereas TREM1 is a crucial mediator of septic shock that acts by synergizing with Toll-like receptors (TLRs) to amplify the inflammatory responses to pathogens, thus promoting sepsis-induced immune dysregulation and organ dysfunction." (PMID 38283341, 2023). "A2M, IL1F10, SYT13, and TREM1 emerge as compelling biomarkers for sepsis and trauma based on their distinct roles in immune response modulation." (PMID 38283341, 2023). "At the early time point, SYT13 and IL1F10 displayed a minimum 2-fold shift increase in expression levels in sepsis patients when compared to trauma patients." (PMID 38283341, 2023). "Distinct patterns emerged with increased SYT13 and IL1F10 levels in plasma samples from sepsis patients, while A2M levels were decreased when compared to the level detected in plasma samples from trauma patients." (PMID 38283341, 2023). "Our analysis showed enhanced levels of SYT13, IL1F10, and S100A10 cytokines in early sepsis patients, while TREM1 levels in trauma patients increased gradually over time." (PMID 38283341, 2023). "SYT13 and IL1F10 emerged as potential early sepsis biomarkers, while reduced levels of A2M were indicative of both trauma-induced inflammation and sepsis conditions." (PMID 38283341, 2023). "To validate our findings, we extended the number of plasma samples for trauma (n = 23) and sepsis patients (n = 23) and performed quantitative ELISA to measure the contents of A2M, IL1F10, SYT13, and TREM1 in these samples at three time points (day 0, 3 and 5)." (PMID 38283341, 2023). "Interestingly, IL1F10 positivity was also observed in SYT13-negative samples, suggesting the complexity of biomarker interactions in sepsis cases." (PMID 38283341, 2023). "To conclude, our research emphasizes the potential of A2M, IL1F10, SYT13, and TREM1 as a composite set of biomarkers for distinguishing between non-infected trauma and sepsis patients." (PMID 38283341, 2023).
small bowel neuroendocrine tumors (1 paper, 2021). "In small bowel neuroendocrine tumors, SYT13 has been reported to be involved in metastasis by interacting with the AKT pathway." (PMID 34677264, 2021).
synucleinopathies (1 paper, 2025). "The present study provides new insights into the dysregulation of extracellular vesicle release associated with SYT13 in synucleinopathies." (PMID 40551252, 2025). "Conversely, in the advanced stages of human synucleinopathies, we observed a significant reduction in SYT13 mRNA expression." (PMID 40551252, 2025). "This interaction between abnormal α-Syn and SYT13 resulted in impaired vesicle release in synucleinopathies." (PMID 40551252, 2025). "Abnormal α-Syn impairs extracellular vesicle release through interactions with SYT13 in synucleinopathies." (PMID 40551252, 2025). "To qualitatively investigate the changes in SYT13 in synucleinopathies, we performed fraction analysis (DLB n = 3 and control n = 3; MSA n = 3 and control n = 3) using the human temporal lobe homogenates." (PMID 40551252, 2025). "The results from transcriptomic, immunohistochemical, and immunoblotting analyses indicated the involvement of SYT13 in the pathogenesis of synucleinopathies." (PMID 40551252, 2025). "As α-Syn is an intrinsically disordered synaptic protein that frequently interacts with other proteins under pathological conditions, we speculated that abnormal α-Syn may interact with SYT13 in synucleinopathies." (PMID 40551252, 2025). "We also elucidated that toxic α-Syn oligomers might dysregulate extracellular vesicle release through binding to SYT13 in the brains of individuals with synucleinopathies." (PMID 40551252, 2025). "Finally, we investigated SYT13 mRNA expression levels in the brains of individuals with synucleinopathies." (PMID 40551252, 2025). "In addition, abnormal α-Syn interacted with SYT13 at the synapse, which led to the dysregulation of the release of extracellular vesicles in synucleinopathies." (PMID 40551252, 2025).